CXCR4 (C-X-C motif chemokine receptor 4)
Diseases named in the same sentence as CXCR4 in open-access papers (continued):
Sharing a sentence is not in itself a finding about the gene and the disease.
tumor (continued). "In conclusion, our multivariate analysis revealed a significant association between MRP2, CXCR4, and PD-L1 co-expression and an improved prognosis for GBC patients, regardless of tumor staging." (PMID 37444550, 2023). "Next, the results of cell-cell communication analysis suggested that pericytes interact with broad immune cells via MDK-NCL pathways in metastasis samples, MIF-(CD74+CXCR4) and MIF-(CD74+CC44) interaction especially occurred between different cell types in tumor and normal samples." (PMID 37335089, 2023). "We investigated whether the CXCL12/CXCR4 axis-mediated transformation of ADMSCs promotes the migration and invasion ability of MCF7 cells and whether curcumin reverses this tumor-promoting effect." (PMID 38004606, 2023). "Multivariate analysis including established prognostic markers (high tumor stage, positive lymph node status, venous invasion, lymphovascular invasion, sarcomatoid differentiation, and grading > G2) did not confirm CXCR4 as an independent prognosticator." (PMID 36982302, 2023). "The differentiation of CAFs gradually increases during tumor progression and may depend on the combined stimulation of TGF-β and SDF-1/CXCR4 autocrine signaling loops in CAFs to maintain stable differentiation." (PMID 37496657, 2023). "Not only that, they also found that renal CSCs were positive for C-X-C motif chemokine receptor 4 (CXCR4), mesenchymal-epithelial transition factor (MET) and homing cell adhesion molecule (CD44), which accounted for an average of 2.2% of the total tumor cells." (PMID 37025584, 2023). "In separate experiments, mice were treated with local 12 Gy RT of the tumor, with or without systemic CXCR4 inhibition, and followed for a longer period of observation." (PMID 36831366, 2023). "Sytl1, a Rab27b partner in hematopoietic cells, facilitates CXCR4 membrane trafficking and promotes occupancy of the bone marrow niche by AML, indicating the importance of the Rab27/Sytl axis in the interaction between tumor cells and the microenvironment." (PMID 37029109, 2023). "In addition to its influence on cancer–neuronal crosstalk and tumor growth, the CXCL12/CXCR4 axis is also important for immune cell migration and possibly plays a role in modulating the response to immunotherapy." (PMID 37834436, 2023). "The main finding of our study is that the close margin, defined as tumor-free by the conventional histopathological examination, may show high levels of SOX2, CD44, and CXCR4 to an extent comparable to that observed in the relative tumor core." (PMID 38096163, 2023). "In SPECT/CT imaging studies, 99mTc-AMD3465 exhibited a higher tumor uptake in CXCR4-positive MCF-7 tumor xenografts compared with those in CXCR4-negative CHO tumors." (PMID 37375261, 2023). "Then, we investigated whether the TC microenvironment could recruit mast cells to the tumor stroma by chemotaxis by screening the chemokine receptors involved in mast cell migration, including CCR2, CCR5, CXCR1, CXCR2, CXCR4, and CXCR7." (PMID 37042867, 2023). "Since CXCR4 was highly expressed across most T cell subsets in BrM.ICB, the MRC1+LYVE1+ macrophage population could recruit these T cells into the BrM tumor parenchyma through CXCR4:CXCL12 interactions." (PMID 37655659, 2023). "In addition, tumor cell infiltration requires a unidirectional transition from migratory to perivascular macrophages, which is regulated by CXCL12 and CXCR4." (PMID 36173487, 2023). "In addition, Tec family tyrosine kinases can activate C-X-C chemokine receptor type 4 (CXCR4), which affects tumor growth, survival, and migration." (PMID 36903645, 2023). "In addition to cell mobilization from BM, the CXCL12/CXCR4/CXCR7 axes can participate in the growth and development of tumor cells and angiogenesis." (PMID 38260135, 2023).
tumor (continued). "Although CXCR4 expression is ubiquitous in hematopoietic and non-hematopoietic cells, it is upregulated in MM cells by several tumor microenvironment-related factors, including hypoxia and pro-inflammatory cytokines." (PMID 37629558, 2023). "Indeed, it has been suggested that tumor growth was associated with accumulation of regulatory B cells (Breg) within TDLNs, which in turn could promote cancer cells recruitment via the production of anti-HSPA4 immunoglobulin and the activation of the CXCL12/CXCR4 pathway." (PMID 38074683, 2023). "Chemokines and their related receptors are another important hypoxic hotspot, which in turn affect tumor endothelial cells and increase the over expression of VEGF, CXCL12, and its receptor CXCR4, making all of them function on endothelial cells in an autocrine way." (PMID 37056346, 2023). "Thus, the CXCR4 blockade by NPs abolished GBM proliferation, decreased infiltration of CXCR4+ monocytic myeloid-derived suppressor cells (M-MDSCs) into the tumor, and restored BBA integrity." (PMID 38004925, 2023). "The staining of non-tumor tissue for CXCR4 revealed a negative cytoplasmic stromal cell expression, with an increase in CXCR4 staining in the cytoplasm of stromal cells in tumor pancreatic tissue." (PMID 37697316, 2023). "Specifically, CXCR4 is overexpressed in glioblastoma progenitor cells, and in OSCC, CXCL12 secreted from CAFs recruits monocytes with M2 macrophage behaviors, considerably increasing CSC expansion and inhibiting tumor cell apoptosis." (PMID 37784157, 2023). "Interestingly, TAM-derived TNF-α was also suggested to be involved in EMT-independent mechanisms for metastasis, characterized by CXCR4-overexpressing endothelial cells evident in murine and human HCC termed “vessels that encapsulate tumor clusters” (VETC)." (PMID 36845555, 2023). "Additionally, IL-19 involved the role of MMP2, IL-6, MMP9, IL-1β, CXCR4, fibronectin, and TGF- β for tumor development." (PMID 37675062, 2023). "Notably, high levels of SOX2, BMI1, and CXCR4, as well as low levels of UBE2C in the tumor core (T) significantly correlate with a greater tumor size and lymph node compromise." (PMID 38096163, 2023). "The newly synthesized CXCR4 antagonist, PRX177561, significantly attenuates GBM tumour growth and might augment the effects of antitumour chemotherapy and radiation therapy (RT)." (PMID 36140541, 2022). "Given the frequent concurrent up-regulation of CXCR4/ACKR2 and ErbB family receptors in BC and their shared relevance for tumor growth and metastasis occurrence, investigating their interplay mechanisms in tumor contexts is of utmost importance." (PMID 36233192, 2022). "Moreover, BoxA, a fragment of HMGB1 that corresponds to its first HMG domain, can also bind to CXCR4 and promote CXCR4-CD47 co-internalization and tumor cell phagocytosis." (PMID 35565443, 2022). "Many studies have shown that CXC chemokines attract neutrophils to tumor tissues, promote neovascularization, enhance the expression of pro-metastatic genes (e.g., SPARC, CXCR4, PTGS2/COX2, ANGPT, ALDH, EREG, and EFEMP), and thereby produce a pro-metastatic microenvironment." (PMID 36612163, 2022). "We observed an increase in the expression of specific markers such as Caldesmon 1 (CALD1) (p = 0.0188), Tumour Endothelial Marker 8 (TEM8) (p = 0.0001) and C-X-C motif chemokine receptor 4 (CXCR4) (p = 0.0048) when CAM was treated with the pro-angiogenic VEGF at 200 ng/mL." (PMID 35644891, 2022). "In addition, through PI3K/AKT signaling, CXCL12 and its specific receptor CXCR4 have been shown to increase VEGF synthesis mediated by GSCs and tumor angiogenesis." (PMID 35269652, 2022). "Along these lines, a recent publication in 90 patients with histologically proven solid cancers undergoing CXCR4-targeted PET/CT 42 also reported no relevant tumor sink effect." (PMID 35966583, 2022).
tumor (continued). "Even though, in our study, CXCR4 expression was not correlated with the depth of tumor invasion (pT), its expression rate was higher in advanced TNM-staged cancers." (PMID 35877436, 2022). "For example, stromal-derived factor 1 (SDF-1/CXCL12) secreted by CAFs promotes bone metastasis by interacting with cancer cells through CXCR4, while CAFs-secreted epidermal growth factor receptor (EGFR) can promote bone metastasis by directly interacting with tumor cells." (PMID 36237303, 2022). "In another study, CAF has been shown to induce HIF-1α-dependent oxidative response, thereby increasing the expression of CXCR4 and interleukin-6 (IL-6) receptors in prostate cancer cells to promote epithelial-to-mesenchymal transition (EMT) and invasion of the tumor cells." (PMID 35884382, 2022). "Tumour tropism of MSCs is well established and involved the SDF-1/CXCR4 axis." (PMID 36376945, 2022). "In GC, this positive effect on tumor cell proliferation of CAFs might be mediated by CAF-released dipeptidyl peptidase-4 (DPP-4) and its receptor, C-X-C chemokine receptor 4 (CXCR4), which is present in tumor cells." (PMID 36244987, 2022). "Furthermore, BC-MSCs recruit CXCR2+ neutrophils into TME, inducing a significant increase in expression of metastasis-related genes (CXCR4, CXCR7, MMP12, MMP13, IL-6 and TGF-β) in tumor cells and consequent metastasis." (PMID 35842634, 2022). "Under inflammatory conditions, neutrophils release a variety of cytokines, one of which is CXCL12, which was significantly elevated in tumor supernatant from B16.BL6-bearing mice that had been treated with anti–CTLA-4 and 7HP349, for which chemokine receptor CXCR4 is expressed on CD8+ Teffs." (PMID 35552271, 2022). "Finally, expression and signaling of the CXCR4/CXCL12 axis in both immunosuppressive and effector immune cells regulate the balance of pro- and antitumor leukocytes recruited to a tumor." (PMID 36293358, 2022). "The results not only pointed out the potential of CXCR4 as a marker of breast CSCs but also provided evidence for the transformation of non-stem tumour cells to stem cells." (PMID 35563449, 2022). "Fittingly, CXCL12 methylation downregulates tumor intrinsic CXCL12 protein expression, disrupting cellular feedback mechanisms to internalize membranous CXCR4 in PCa, thereby fostering metastasis, which is suggestive of the possible therapeutic potential of CXCL12 inhibitors." (PMID 35406450, 2022). "Additional in vitro experiments demonstrated that activated B cells provoked direct cytotoxic action on tumor cells through CXCR4/CXCL12 pathways, while without cell contact, B cell-secreted perforin also led to tumor cell cytotoxicity." (PMID 35967441, 2022). "In addition, CAFs nourish CXCR4+ pancreatic cancer stem cells by producing its ligand CXCL12, promoting tumor cell growth and gemcitabine resistance via activation of FAK, AKT and ERK signaling pathways." (PMID 36230914, 2022). "It is particularly noteworthy that 6 chemokine receptors in GO term “chemokine binding”, including CXCR4, CCR5, CCR1, CCRL2, CMKLR1 and A2M, are specific expressed in FGFR2+ fibrocytes before arriving in tumor sites suggesting their possible roles in fibrocyte recruitment." (PMID 35941662, 2022). "In our study, the expression of CXCR4 did not correlate with tumor size, location, grade, or Lauren classification." (PMID 35877436, 2022). "By encapsulating si-survivin by electroporation, MSC EVs expressing CXC chemokine receptor type 4 (CXCR4) can specifically bind to the highly expressed stromal cell-derived factor-1 (SDF-1) on the tumor surface, reach the tumor site, knock down the survivin gene, and achieve a tumor-killing effect." (PMID 36297672, 2022). "In addition, tumor hypoxia induces the expression of CCL28, CXCL12 and CXCR4, selectively enhanced the recruitment of T(reg) cells, thereby inducing tumor tolerance and new angiogenesis." (PMID 36226050, 2022).
tumor (continued). "Activation of CAFs by inhibiting different signaling pathways including nuclear factor kappa B (NF-kβ), C-X-C chemokine receptor 4 (CXCR4), fibroblast growth factor receptor (FGFR), and Hedgehog using selective inhibitors showed tumor suppressive or antitumor activity." (PMID 36686754, 2022). "Some researchers have suggested that CXCR4-overexpressing cells downregulate the expression of cyclin D1 and Bcl-2 and activate other signaling pathways such as MAPK to support cell proliferation and tumor progression." (PMID 35941537, 2022). "However, the addition of CXCR4 overexpression and CXCL12 further enhanced the increased migration capacity of SK-Hep1 cells induced by tumor-derived DNA." (PMID 35860597, 2022). "Therefore, small molecule antagonists of CXCR4, such as ALX40-4C, AMD3100, and BKT140, have been used in tumor-related treatments." (PMID 35770088, 2022). "Our study used CXCR4 and CXCL-12 to model the tumor microenvironment versus drug response." (PMID 36551144, 2022). "Moreover, their experimental results of using the CXCR4 antagonist AMD3100 or knocking out the CXCR4 gene showed that VEGF expression was reduced and tumorigenesis and angiogenesis was inhibited in a nude mouse lotus tumor model." (PMID 35770088, 2022). "We also showed that CAF-derived soluble factors downregulated the expression of CXCR3 on CD4+ and CD8+ T cells and CCR5 on CD8+ T cells and upregulated the expression of CXCR4 on CD4+ and CD8+ T cells, potentially affecting their migratory capacity towards tumor cells." (PMID 35954489, 2022). "In this regard, the G protein-coupled receptor kinase 2 (GRK2) can act as regulator of both G protein-coupled receptors (GPCRs), including CXCR4/ACKR3, and GFR of the receptor tyrosine kinase (RTKs) family, and has emerged as a critical signaling hub involved in orchestrating most tumor hallmarks." (PMID 36233192, 2022). "The results showed that TTCS induced significantly more tumor‐infiltrating neutrophils to migrate than NTCS from the same GC patients, and such migration was blocked upon pre‐treatment with neutralizing antibodies against CXCL12 and/or CXCR4." (PMID 34957697, 2022). "Tumor cells in advanced cervical cancer, malignant pleural mesothelioma, ovarian cancer and renal cell carcinoma secrete CXCL12, which recruits both TAMs and T-regulatory cells (Tregs) via binding to CXCR4 expressed at high levels on their surface." (PMID 35565443, 2022). "We designated “ImmunoGenic Surrender” (IGS), the mechanism whereby CXCR4 engagement drives CD47 surface depletion and eventually the appearance of tumor-specific CD8 T cell clones, as the tumor cells surrender to macrophages, which phagocytose them when still alive." (PMID 35565443, 2022). "Furthermore, upregulation of Cxcr4 and Cxcl2, and H2-Aa by PTT+GC treatment indicates an increase in antigen presentation and pro-inflammatory functions of the tumor-infiltrating B cells." (PMID 34976205, 2022). "This platform aims to deliver the cytotoxic compound selectively to CXCR4-overexpressing cancer cells without off-target toxicity in non-tumor bearing organs." (PMID 35456719, 2022). "Another miR might be involved in the regulation of CXCR4, miR-622, which is underexpressed in CRC metastases and has been described as a potential tumor suppressor gene by slowing down KRAS-dependent tumor and metastasis formation in mice." (PMID 35406582, 2022). "To summarize, our results suggest that certain CAF-derived soluble factors downregulated the expression of CXCR3 on CD4+ and CD8+ T cells and CCR5 on CD8+ T cells and upregulated the expression of CXCR4 on CD4+ and CD8+ T cells, which affect their migratory capacity towards tumor cells." (PMID 35954489, 2022).
tumor (continued). "Seventy-eight cores (18%) were scored CXCR4 negative (no staining at all), and 18 cores (4.2%) had both strong staining as well as > 75% staining of the tumor cells." (PMID 33550492, 2022). "In addition, USP14 deubiquitinates and increases the stability of C-X-C Motif chemokine receptor 4 (CXCR4), which is highly expressed in tumors and plays an important role in tumor immune suppression." (PMID 36163134, 2022). "Except for fibroblasts, a total of 937 endothelial cells were also obtained, which were subclustered into five subsets, including extra-alveolar capillary ECs (Endo-C1; EDN1+), tumor ECs (Endo-C3; INSR+), and other ECs (Endo-C2, ICAM1+; Endo-C4, MAP1B+; Endo-C5, CXCR4+)." (PMID 36046337, 2022). "Conversely, CXCR4 overexpression strikingly counteracted the effect of PTX on decreasing Akt phosphorylation and reductions in N-cadherin, vimentin, snail, CD44, CD133, and NANOG protein expression in SKOV3 tumor tissues (*P<0.05)." (PMID 35681259, 2022). "Targeting TGF-β could weaken both the expression of CXCR4 and activation of TβR–Smad signaling in stromal fibroblasts, thus hindering the feedback loop of TGF-β and SDF-1 and blocking the activation of tumor-promoting CAFs." (PMID 35681617, 2022). "Furthermore, these nanocomplexes significantly inhibited CXCR4 and down-regulated CD44 expression, thus exhibiting a potent tumor-killing ability and inhibition of the metastatic and invasive activity of cancer cells." (PMID 35893797, 2022). "RCC is a highly vascularized tumour, in which the von Hippel Lindau tumour suppressor gene is frequently inactivated, leading to the overexpression of the hypoxia-inducible factor (HIF)-2α oncoprotein and CXCR4 overexpression." (PMID 36140541, 2022). "Comparison of all three sample types (fluid, tumor tissue and PBMCs) identified only 2 DE genes—CXCR4 and IFIT1—which do not show concordant expression between samples." (PMID 36428740, 2022). "In addition, sorafenib treatment was found to increase hypoxia and SDF1α/CXCR4 expression in HCC cells and animal tumor models, whereas inhibition of the SDF1α/CXCR4 pathway overcame the sorafenib resistance in HCC." (PMID 36071839, 2022). "Malignant cells in the tumors generate TGF-β, thus upregulating CXCR4 on the monocyte cell surface, whereas perivascular fibroblasts produce the CXCR4 ligand CXCL12 to target these monocytes to the tumor, followed by monocytes differentiating into perivascular macrophages." (PMID 35720407, 2022). "To determine whether CXCR4 expression plays an important role in limiting PTX chemotherapy sensitivity in vivo, we developed CXCR4-Kd#2/OVCA420 and CXCR4/SKOV3 cell line-xenograft tumor nude mouse models." (PMID 35681259, 2022). "The tumour migratory efficiency and percentage of CXCR4 population did not change when stored in CS10." (PMID 36376945, 2022). "Notably, CXCR4/CXCL12 cross-signal via the T and B cell receptors (TCR and BCR) and co-internalize with CD47, promoting tumor cell phagocytosis by macrophages in an anti-tumor immune process called ImmunoGenic Surrender (IGS)." (PMID 35565443, 2022). "Thus, targeting the CXCR4/CXCL12 axis can optimize intratumoral T cell localization, promote T cell anti-tumor activity, and enhance the efficacy of ICB and cytotoxic chemotherapy." (PMID 33603130, 2022). "Moreover, we demonstrated a CXCR4-dependent biodistribution for the T22-GFP-H6 nanocarrier, and its enhanced uptake in tumor tissue in a subcutaneous EC model." (PMID 36612081, 2022). "More importantly, CXCR4 directly controlled cell proliferation of non-hematopoietic cells and tumor cell growth and transduced signaling through mTOR pathway." (PMID 36163180, 2022). "However, in line with the observations above, when CAFs were added to the cultures together with tumor spheroids, a decrease in CXCR3 expression and an increase in CXCR4 expression was observed in CD8+ T cells." (PMID 35954489, 2022).